INS (insulin)
Diseases named in the same sentence as INS in open-access papers (continued):
Sharing a sentence is not in itself a finding about the gene and the disease.
Obesity (continued). "The altered responses of insulin-antagonistic hormones and the glucose fluctuations that exist due to obesity and hyperglycemia may modify the acute responses to exercise and exercise tolerance." (PMID 33870263, 2021). "Interestingly, NOX inhibition improves adipokine secretion and increases insulin sensitivity via restoration of normal ROS production in adipocytes from individuals with obesity." (PMID 33921645, 2021). "In conclusion, our data did not support beneficial effects on obesity and insulin sensitivity described for other Adcy5-deficient mouse models." (PMID 33919448, 2021). "Further, the obesity-induced reductions in adipocyte autophagy were reversible and improved after bariatric surgery (a strategy that diminishes energy intake and restores systemic insulin sensitivity)." (PMID 34336862, 2021). "Early on, even prior to the clinical diagnosis of T2DM, there may be variable degrees of obesity, insulin and leptin resistance and impaired glucose tolerance." (PMID 34063911, 2021). "In contrast, overexpression of VEGF-D in adipose tissue induced lymphangiogenesis in adipose tissue of mice, enhanced glucose clearance, and reduced insulin level and liver triglyceride, thereby resisting obesity-related immune accumulation and improving metabolic response." (PMID 34504884, 2021). "In diabetes and obesity, excess insulin, branch chain amino acids, and ATP activate mTOR." (PMID 34987473, 2021). "A high content of butyrate prevented diet-induced obesity and increased insulin sensitivity." (PMID 33921314, 2021). "A high FII may be due to the stimulation of insulin secretion and, thus, an increase in fat synthesis and carbohydrate oxidation, leading to obesity or overweight." (PMID 34221261, 2021). "Impaired insulin signaling is a common feature of the pathophysiology of human obesity and T2DM." (PMID 34071721, 2021). "M. funiformis and F. mortiferum belong to Gram-negative bacteria, which their cell walls contain more lipopolysaccharides that can induce or aggravate the host to produce inflammatory response and insulin resistance, thus involving in the occurrence and development of obesity." (PMID 33717692, 2021). "There is interest in comparing the breeds of ponies and horses that typically present with obesity and insulin dysregulation with reference breeds such as Thoroughbreds and Standardbreds, to understand the physiology that underpins differences in metabolic phenotype." (PMID 35051099, 2021). "For example, a clinical study suggested that downregulation of insulin signaling may occur during obesity before T2DM is developed due to hyperactivation of PH domain leucine-rich repeat-containing protein phosphatase (PHLPP-1)." (PMID 34956089, 2021). "Obesity and overweight, along with positive family history, are the main risk factors for T2DM that is characterized by hyperglycemia with normal or high insulin serum levels, related to a peripherical resistance to insulin signal." (PMID 34438518, 2021). "Subjects with PWS showed lower visceral adiposity compared to subjects with simple obesity and this could account for the higher insulin sensitivity detected in subjects with PWS and less prevalence of dyslipidemia." (PMID 33891302, 2021). "Furthermore, genistein reduced weight gain and prevented obesity in these rats and improved the insulin sensitivity of peritoneal white adipose tissue by increasing the IRS1 and p-AKT levels." (PMID 34641407, 2021). "In the unmatched original cohort, the values of standardized difference were >10% for age, dyslipidemia, obesity, nephropathy, eye diseases, insulin, meglitinide, acarbose, rosiglitazone, pioglitazone, statin, and fibrate, suggesting potential residual confounding from these variables." (PMID 34439890, 2021). "Furthermore, SHBG was strongly associated with both insulin sensitivity (HOMA-IR and WBISI) and insulin secretory (IGI) indexes in children with obesity." (PMID 33689083, 2021).
Obesity (continued). "To evaluate whether obesity was an interference factor between the two groups, we analysed the weight, height, and fasting insulin and fasting blood glucose levels of the patients and calculated their BMI." (PMID 34178894, 2021). "Obesity and its associated comorbidities (including T2D and CVD) are associated with a state of chronic low-grade inflammation that is well-recognized as a major cause of decreased insulin sensitivity." (PMID 33717095, 2021). "Obesity is a leading factor of insulin and IGF resistance along with chronic inflammation." (PMID 35118400, 2021). "This conclusion is very significant because for the treatment of patients with IMF associated with obesity and detected IR (based on HOMA-IR models and Caro index), insulin sensitizers are often used, including metformin, the indications of which in children and adolescents are limited." (PMID 35126755, 2021). "Similar results have been observed in humans, where obesity developed after fecal microbiota transplantation from overweight donors, whereas transplantation of lean microbiotas into individuals with MetS improved insulin sensitivity." (PMID 33919016, 2021). "In addition, women with obesity treated for gestational diabetes with insulin were found to have increased levels of placental lactogen." (PMID 33743677, 2021). "As a result, 4E-BP1 is a gender-specific obesity suppressor that regulates insulin sensitivity." (PMID 34220716, 2021). "Furthermore, brown adipose tissue (BAT) has metabolic functions such as secretion of BATokines, thermogenesis and serves as metabolic sink for glucose and lipids resulting in decreased obesity and increased insulin sensitivity." (PMID 33861726, 2021). "However, many studies on the expression of insulin signaling participants during obesity and T2DM were carried out." (PMID 34956089, 2021). "This may contribute to further metabolic adaptations observed in obesity and prediabetes states, such as inhibition of active fatty acid oxidation, mitochondrial stress and impaired insulin sensitivity, and ultimately impaired glucose homeostasis." (PMID 34711878, 2021). "Finally, very recently in a small study, the 11β-hydroxysteroid dehydrogenase (11BHSD) type 1 (11BHSD1) inhibitor S-707106 demonstrated an effective insulin sensitizer, anti-sarcopenic and anti-obesity effect in both CS and mHC patients." (PMID 34768949, 2021). "The maintenance DNA methyltransferase DNMT1 via CpG promoter methylation epigenetically controls the expression of important developmental genes involved in mTORC1 signaling including insulin (INS), IGF-1 (IGF1), and fat mass- and obesity-associated gene FTO (FTO)." (PMID 33494388, 2021). "Moreover, even after adjusting for obesity, significant relationships between insulin and the other factors have been observed." (PMID 33597002, 2021). "The knockout of NPR3 in adipocytes, but not in skeletal muscle, resulted in a resistance to diet-induced obesity, increased energy expenditure, improved insulin sensitivity, increased glucose uptake, as well as protection from liver steatosis and visceral fat inflammation." (PMID 33206203, 2021). "These improvements in insulin markers in the population with obesity are important because are against of obesity pathophysiology, that is characterized by a state of low-grade systemic inflammation due to increased secretion of inflammatory cytokines, such as TNF-α and IL-6." (PMID 34568974, 2021). "Family history, ethnicity, prenatal and postnatal nutrition, obesity, pubescence, eating habits, and sedentary lifestyle may affect insulin sensitivity in the pediatric population." (PMID 33494341, 2021). "The insulin/IGF-1 system is one of the potential “engineers” of many obesity related cancers." (PMID 34208601, 2021). "Additionally, in hyperinsulinemic conditions, such as obesity, insulin has been attributed a role in attenuating the postprandial drop in ghrelin levels." (PMID 33411809, 2021).
Obesity (continued). "In this perspective, programming of altered brain glucose metabolism and insulin sensitivity might be factors favoring onset of obesity and metabolic abnormalities in these individuals." (PMID 33879765, 2021). "Factors that could contribute to the insulin sensitivity indices include study duration, dosage, and the type of diet used to induce obesity (fructose, sucrose, and fat), weight gain, age, and baseline insulin sensitivity." (PMID 34943108, 2021). "Examination of the isolated compounds, rutin and Q3G, for antidiabetic or anti-obesity properties or both in 3T3-L1 adipocytes demonstrated that they both improved glucose uptake via Akt-mediated insulin signaling pathway or AMP-activated protein kinase (AMPK) activation in 3T3-L1 adipocytes." (PMID 33918969, 2021). "A significant change in insulin sensitivity in individuals living with obesity following SIT was observed compared to individuals living without obesity; however, this finding was likely due to a 25% reduction in insulin sensitivity for individuals without obesity." (PMID 34110721, 2021). "NLRP3 activation impairs insulin sensitivity in dietary-induced obesity." (PMID 33435142, 2021). "Furthermore, many efforts have been made to identify the key factor for obesity-induced cancer, including insulin resistance, increased steroid hormones and adipokine, and aberrant inflammation." (PMID 34884489, 2021). "PR was defined as insulin-dose adjusted HbA1c of ≤9, and obesity as a BMI ≥30 kg/m2." (PMID 34899592, 2021). "Furthermore, IGFBP‐2 is known to be suppressed by GH, insulin, and obesity and has been positively correlated with insulin sensitivity." (PMID 34811874, 2021). "Specifically, lipid metabolism disorder parallel obesity and can impede insulin signaling." (PMID 33802371, 2021). "AT becomes dysfunctional in obesity and generates a pro-inflammatory, hyperlipidemic, and insulin-resistant environment, which ultimately leads to the development of metabolic complications (e.g., diabetes) and cardiovascular complications (e.g., atherosclerosis)." (PMID 34277732, 2021). "Our data suggest that MET may increase liver uptake of amino acids and bumetanide in the improvement of insulin sensitivity and obesity." (PMID 34659115, 2021). "The excessive accumulation of insulin inhibits the proliferation of Treg cells, thus reducing IL-10 production, and the decreased number of Treg cells in obesity leads to decreased IL-10 secretion; thus, insulin further exacerbates the development of obesity-associated AT inflammation." (PMID 34515616, 2021). "Second, obesity-induced chronic inflammation and disruptions of insulin and leptin signaling can result in impaired viral clearance and a disproportionate or hyper-inflammatory response, which together with elevated ferritin levels can be a direct cause for ARDS and cytokine storm." (PMID 33920604, 2021). "Conversely, several studies have illustrated the health benefits of the dietary consumption BCAAs, including enhanced insulin sensitivity, improvement of glucose disposal, enhanced muscle development, obesity management, and an improvement in overall health when coupled with an active lifestyle." (PMID 34209599, 2021). "Given that implantation of photoactivated ASCs could improve glucose tolerance and insulin sensitivity in obesity, we asked whether photoactivation could directly act on glucose uptake to induce insulin-AKT signaling." (PMID 34266493, 2021). "Interestingly, studies have shown that EA at ST36, SP6, CV4, and CV12 decreases the levels of serum insulin and reduces body weight in obese rats, and that EA of 100 Hz is more effective than 30 Hz in reversing obesity." (PMID 33868169, 2021). "Additionally, the state of chronic inflammation related to obesity impacts ovarian physiology due to insulin sensitivity impairment." (PMID 34071499, 2021).
Obesity (continued). "In addition, a new study would allow us to refine our model by including other obesity-related parameters such as insulin sensitivity and circulating levels of apelin expression." (PMID 33972642, 2021). "Common markers for obesity include weight and fasting serum levels of glucose and insulin." (PMID 34071903, 2021). "SPF mice that received microbiota from obese donors did not exhibit an obesity-associated insulin resistant phenotype." (PMID 33692965, 2021). "In obesity, the excessive amount of fat exceeds the ability of skeletal muscles to oxidize this energy substrate, which leads to the development of lipotoxicity and disruption of the physiological muscle function, including impaired insulin signaling." (PMID 34064937, 2021). "Thus, manipulation of sphingolipid levels with drugs or nutrients can be useful approaches for the treatment of obesity by clinicians, particularly by aiming to decrease ceramide levels to have a positive effect on insulin/leptin resistance." (PMID 34069652, 2021). "Interestingly, exercise-induced weight reduction is superior to dieting for improving insulin resistance in individuals with obesity." (PMID 34488728, 2021). "In fact, in participants with obesity, insulin levels were already increased in the fasting state, rose nearly twice as high after glucose consumption, and remained elevated for nearly one hour longer compared to lean individuals, resulting in an inhibition of lipolysis." (PMID 33922802, 2021). "Insulin transport into the brain is decreased with obesity and peripheral insulin resistance." (PMID 34545146, 2021). "In obesity, tissue insulin resistance creates demand upon the β cell to enhance insulin release." (PMID 34064822, 2021). "Our results here indicate that SM levels were significantly up-regulated in the HFD, compared to the SND rabbit groups, in agreement with reports of obesity and insulin sensitivity in obese adult humans and a study on the plasma metabolic fingerprints of atherosclerosis rabbits." (PMID 34438746, 2021). "While HIIT seems preferable at Fatmax when compared to moderate-intensity training, only the latter induced a significant reduction in fasting insulin and insulin resistance, suggesting the importance of exercise duration for improving insulin sensitivity in subjects with obesity." (PMID 34047810, 2021). "The obesity phenotype resulted in decreased response to insulin measured by ITT." (PMID 33716957, 2021). "Therefore, the purpose of this study is to explore the role of leucine and exercise in adiposity, systemic insulin resistance, and inflammation to provide theoretical and guiding basis for the early prevention and treatment of obesity." (PMID 34054726, 2021). "However, further researches are mandatory to convincingly disclose the effects of the insulin/IGF-1 or adiponectin signaling pathways on ISCs response in obesity regarding tumor initiation." (PMID 33827616, 2021). "Despite these limitations, the sOE mice maintained their resistance to diet-induced obesity, and still exhibited reduced fat mass and improved glucose tolerance and insulin sensitivity after the 12 weeks of high-fat feeding, despite consuming more food than controls." (PMID 34588527, 2021). "Interestingly, in eIF2α-mutant mice that developed severe obesity associated with a reduced metabolic rate, GRP78 effectively reduced insulin levels and participated in adipogenesis and glucose homeostasis in adipose tissues when fed a high-fat diet." (PMID 34359881, 2021). "Elevated CRP, symptomatic of obesity, may signify an overproduction of proinflammatory cytokines that directly impinge on the insulin signal transduction pathway." (PMID 34769939, 2021). "Skeletal muscle is another insulin responsive tissue that is impaired in obesity and diabetes." (PMID 34957242, 2021).
Obesity (continued). "Nonetheless, a positive association between SLC16A11 risk genotypes with BMI and insulin was found in nondiabetic individuals, which indicates that the SNP can be considered an early risk marker for obesity and T2D." (PMID 33909378, 2021). "Likewise, many hormones—such as insulin—influence reinforcement, raising the possibility that metabolic dysfunction in obesity influences the effect of macronutrients on reward coding." (PMID 33917347, 2021). "The same low-volume HIIT protocol has also been demonstrated to improve insulin sensitivity, measured with the hyperinsulinemic-euglycemic clamp, 24 h following exercise in adults with overweight/obesity who have recently undergone a 12-week exercise-training program." (PMID 34940959, 2021). "Although it is unknown if the stroke-obesity paradox is related to insulin sensitivity/resistance (IR), IR has been theorized to contribute to this phenomenon." (PMID 33967936, 2021). "Therefore, studies on larger cohorts that differ in age, gender, duration of obesity and insulin sensitivity with longer follow-up are warranted to confirm our results and to more deeply investigate these links." (PMID 34836316, 2021). "As obesity/adiposity might have an impact on insulin secretion and sensitivity, we subdivided the participants according to their BMI." (PMID 33829033, 2021). "Finally, to confirm the roles and effects of miR-23b-3p and NEU1 in mice with obesity-induced IR, we performed glucose and insulin tolerance tests." (PMID 33781239, 2021). "Vaspin-mediated protection of AT from obesity-induced inflammation may contribute to improved insulin sensitivity, as has been shown in adipocytes in vitro." (PMID 33572949, 2021). "Secondly, PTP-1B (protein tyrosine phosphatase 1B) was shown to mainly have adverse effects on leptin transduction and insulin signaling, and the inhibition of this enzyme is reported to speed up the insulin signaling pathways and in turn have positive effects in treating obesity." (PMID 34071722, 2021). "Among them, B. acidifaciens prevents obesity and improves insulin sensitivity in mice." (PMID 35054427, 2021). "AMGB was found to be related to the adipocytokine signaling pathway, implying that AMGB may be beneficial in preventing obesity via regulating insulin and leptin signaling pathways." (PMID 34944525, 2021). "Furthermore, a clear relationship between obesity and insulin levels is still detectable in PWS children, with obese individuals showing higher insulin levels and HOMA-IR than non-obese subjects." (PMID 34884336, 2021). "Insulin was reduced in the exercised obese group (control vs obese P < 0.0001, obese vs exercised obese P < 0.0001, control vs exercised obese P > 0.05), and plasma NA was significantly reduced in obesity, indicating autonomic dysfunction." (PMID 33687595, 2021). "Some studies had indicated that paternal obesity can reduce skeletal muscle insulin sensitivity." (PMID 34836492, 2021). "Additionally, some groups recorded the dual stimulative/inhibitory effect of β-endorphin on insulin secretion depending on dose, obesity, or circulating glucose level." (PMID 34099024, 2021). "Inhibition of IL6 and SOCS3 and facilitation of CNTF could serve as a favorable strategy to enhance insulin action and improve glucose homoeostasis, which are of importance for treating obesity-related disorders for chickens." (PMID 32106651, 2021). "Therefore, the purpose of this study is to discuss the role and possible mechanism of leucine and exercise in adiposity, systemic insulin resistance, and inflammation, and to provide a theoretical basis to guide the prevention and treatment of early obesity." (PMID 34054726, 2021). "Thus, reduced insulin signalling in the larvae fed on a low nutritive diet resulted in obesity and starvation resistance in adult stages." (PMID 33606785, 2021).